LRRC8D (leucine rich repeat containing 8 VRAC subunit D)
Description:
Non-essential component of the volume-regulated anion channel (VRAC, also named VSOAC channel), an anion channel required to maintain a constant cell volume in response to extracellular or intracellular osmotic changes. The VRAC channel conducts iodide better than chloride and can also conduct organic osmolytes like taurine. Plays a redundant role in the efflux of amino acids, such as aspartate, in response to osmotic stress. LRRC8A and LRRC8D are required for the uptake of the drug cisplatin. Channel activity requires LRRC8A plus at least one other family member (LRRC8B, LRRC8C, LRRC8D or LRRC8E); channel characteristics depend on the precise subunit composition. Also acts as a regulator of glucose-sensing in pancreatic beta cells: VRAC currents, generated in response to hypotonicity- or glucose-induced beta cell swelling, depolarize cells, thereby causing electrical excitation, leading to increase glucose sensitivity and insulin secretion (By similarity). VRAC channels containing LRRC8D inhibit transport of immunoreactive cyclic dinucleotide GMP-AMP (2'-3'-cGAMP), an immune messenger produced in response to DNA virus in the cytosol. Mediates the import of the antibiotic blasticidin-S into the cell.
Synonyms: HsLRRC8D; LRRC5; FLJ10470
Tractability: Antibody: UniProt places it where antibodies can reach, with high confidence; its Gene Ontology location is reachable by antibodies, with high confidence; UniProt predicts a signal peptide or a membrane-spanning region. PROTAC: ubiquitination databases record sites on it; its protein half-life has been measured.
Gene: Protein-coding gene on chromosome 1 (89,820,978 to 89,936,611, forward strand). Ensembl gene ENSG00000171492.
Subcellular location: Cell membrane; Endoplasmic reticulum membrane
Pathways (Reactome):
Transport of small molecules: Miscellaneous transport and binding events
Gene Ontology:
Molecular function: protein binding; volume-sensitive anion channel activity
Biological process: aspartate transmembrane transport; cellular response to osmotic stress; cyclic-GMP-AMP transmembrane import across plasma membrane; monoatomic anion transmembrane transport; protein hexamerization; taurine transmembrane transport; intracellular glucose homeostasis
Cellular component: cytoplasm; endoplasmic reticulum membrane; membrane; monoatomic ion channel complex; plasma membrane
Genetic constraint (gnomAD): Loss-of-function variants: 20 observed, 57.92 expected, observed/expected ratio (o/e) 0.35, 90% interval 0.24 to 0.5. The upper end of that interval is the gene's LOEUF score, 0.5, which puts it in group 2 of 6, group 1 being the genes least tolerant of losing a copy. Missense variants: 651 observed, 1,085.6 expected, observed/expected ratio (o/e) 0.6, 90% interval 0.56 to 0.64. Synonymous variants: 352 observed, 399.49 expected, observed/expected ratio (o/e) 0.88, 90% interval 0.81 to 0.96.
Homologues: Orthologues: macaque LRRC8D (99% identical), guinea pig LRRC8D (98% identical), dog LRRC8D (97% identical), mouse Lrrc8d (96% identical), rat Lrrc8d (96% identical), pig LRRC8D (95% identical), rabbit LRRC8D (91% identical), tropical clawed frog lrrc8d (82% identical), zebrafish lrrc8db (77% identical). Paralogues in human: LRRC8A (52% identical), LRRC8C (49% identical), LRRC8E (47% identical), LRRC8B (45% identical), PHLPP1 (16% identical), SCRIB (14% identical), ERBIN (14% identical), PHLPP2 (14% identical), LRRC1 (13% identical), LRRD1 (13% identical), LRRC40 (13% identical), LRRC7 (13% identical), and 19 more.
Diseases named in the same sentence as LRRC8D in open-access papers:
LRRC8D is named in the same sentence as 11 diseases in open-access papers, as found by Europe PMC text mining. Sharing a sentence is not in itself a finding about the gene and the disease. The quoted sentences say what the papers report.
ovarian carcinoma (3 papers, 2015 to 2022). A malignant neoplasm originating from the surface ovarian epithelium. "Using The Cancer Genome Atlas and Patch and colleagues datasets, we have previously reported a lower survival of patients with ovarian cancer who have a low LRRC8D gene expression." (PMID 36467895, 2022).
endometrial cancer (2 papers, 2019 to 2020). Primary or metastatic malignant neoplasm involving the endometrium (mucous membrane that lines the endometrial cavity). "In another study, a six-gene prognostic signature, including CTSW, PCSK4, LRRC8D, TNFRSF18, IHH, and CDKN2A, in endometrial cancer was also established using robust likelihood-based survival modeling." (PMID 31781484, 2019).
Mammary Tumor (1 paper, 2022).
Obesity (1 paper, 2022). Accumulation of substantial excess body fat. "Four of the differentially methylated regions were in genes previously found to be associated with obesity, metabolic regulation, and glycemic control (LRRC8D, SOSTCD1, MORN3, and MCF2)." (PMID 36474183, 2022).
tumor (4 papers, 2015 to 2024). "A comparative analysis of multiple genes revealed that LRRC8A and LRRC8D exhibit higher expression in tumours when compared to other LRRC8 genes, providing an overall characterization." (PMID 38909013, 2024). "Depletion of Lrrc8a or Lrrc8d significantly lowered the tumor response to carboplatin and resulted in a decreased overall survival (OS; P = 0.002 for Lrrc8a, P = 0.0131 for Lrrc8d)." (PMID 36467895, 2022). "The stratification of the tumors into low (N = 61), medium (N = 60), and high (N = 60) LRRC8D gene expression subgroups revealed decreased OS (P = 0.051) and poor tumor progression outcome (P = 0.054) in the low expression group." (PMID 36467895, 2022). "Therefore, inhibition of TauT may inhibit the development of tumor by reducing the expression of Pik3r2.In addition, through proteomic analysis, we found that TauT knockout promoted the expression of Lrrc8d protein." (PMID 35468821, 2022).
cancer (3 papers, 2020 to 2023). A tumor composed of atypical neoplastic, often pleomorphic cells that invade other tissues. "Interestingly, when either LRRC8A or LRRC8D is knocked out, cancer cells exhibit a higher tolerance towards these platinum-based medications." (PMID 37538172, 2023). "Therefore, the expression profile of LRRC8D mRNA may predict the sensitivity of cancer cells to cisPt as described by Planell-Cases and coworkers." (PMID 32485798, 2020).
metabolic disorders (1 paper, 2026). "LRRC8D (leucine-rich repeat-containing 8D) is a component of the volume-regulated anion channel (VRAC), and its mutation or dysregulation is associated with drug resistance and metabolic disorders." (PMID 41601671, 2026).
LRRC8D also shares sentences with these, for which no sentence is quoted: carcinoid tumor (1 paper); epilepsy (1); ovarian germ cell cancer (1); Parkinson disease (1).